PLK1 (polo like kinase 1)
Diseases named in the same sentence as PLK1 in open-access papers (continued):
Sharing a sentence is not in itself a finding about the gene and the disease.
colorectal cancer (continued). "Notably, siRNA-mediated knockdown of XAB2 and PLK1 caused a virtually complete loss of proliferation, extending the known essential functions of these genes also to DLD1 colorectal cancer cells." (PMID 26755646, 2016). "PLK1 expression has also been documented in precursor/early cancers of other organs, such as in ovarian cystadenoma and in early papillary thyroid carcinoma and previously PLK1 over-expressing colorectal cancers have been reported to display a more radioresistant phenotype." (PMID 26047016, 2015). "PLK1 has been reported to be over-expressed in numerous cancer types, such as non-small-cell lung cancer, oropharyngeal carcinoma, esophageal carcinoma, melanoma, colorectal cancer, hepatoblastoma, non-Hodgkin lymphoma, and others." (PMID 24205328, 2013). "Together with the report that PLK1 is overexpressed in colorectal cancers, the majority of which are characterized by dysregulated Wnt signalling, it is of interest to test whether PLK1 plays a role in regulating Wnt/β-catenin signalling in the future." (PMID 23155463, 2012). "The results showed that in colorectal cancer, the expression of SLC35A2 was positively correlated with the expression of four MYC-associated genes, including MYC, Cyclin dependent kinase 4 (CDK4), Polo like kinase 1 (PLK1), and Pescadillo ribosomal biogenesis factor 1 (PES1)." (PMID 40303483, 2025). "Therefore, we aimed to investigate whether inhibition in PLK1 would reduce colorectal cancer cell growth, EMT, and its role in the CRAF-MEK-ERK signaling pathway." (PMID 39451218, 2024). "In addition, positive PLK-1 expression was associated with lymph node metastasis, invasion, and advanced TNM stage, implying that PLK-1 expression could be an important factor in assessing the biological behavior and prognosis of colorectal cancer." (PMID 39857637, 2024). "BI 2536 was the first selective PLK1 inhibitor investigated in clinical trials with patients who have various advanced and/or metastatic solid tumors including non-small cell lung cancer, hepatocellular carcinoma, colorectal cancer, melanoma, and ovarian cancer." (PMID 28724602, 2017). "Nitidine chloride; Polo-like kinase 1; MYCN; Molecular dynamics simulation; Multi-omics; Spatial transcriptomics; Colorectal cancer." (PMID 42205755, 2026). "Recent studies have also found that PLK1 is involved in ferroptosis pathway, and PLK1-CBx8-GPX4 can overcome the drug resistance mechanism of colorectal cancer by inducing ferroptosis." (PMID 40612941, 2025). "Onvansertib is a competitive ATP inhibitor for Plk1 in clinical trials for the treatment of tumors and has recently entered a trial for the treatment of KRAS mutant colorectal cancers (CRCs)." (PMID 40197665, 2025). "In colorectal cancer, increased AXL contributes to the upregulation of TWIST1, which is directly related to EMT and mediates resistance to PLK1 inhibitors." (PMID 37328828, 2023). "In colorectal cancers, AXL induces the expression of Twist family BHLH transcription factor 1 (TWIST1) and mediates resistance to polo-like kinase 1 (PLK1) inhibitor." (PMID 37328828, 2023). "Some studies have shown that BI2536, Volasertib, and GSK461364 can effectively inhibit the expression of PLK1, and BI2536 has entered phase I clinical trials for colorectal cancer, liver cancer, fallopian duct cancer, and other cancers." (PMID 35756492, 2022). "Meanwhile, PLK1 overexpressed in the liver, lung, stomach, and epidermis, BUBR1 (also known as homologue beta) is overexpressed in colorectal cancer, lung, pancreatic tumors, and T-cell lymphoma." (PMID 34834441, 2021). "Hyperactivity of PLK1‐MYC‐CDC7 axis correlates with recurrence and poor prognosis in colorectal cancer." (PMID 34881526, 2021). "For example, kinome-wide siRNA screening results indicate that polo-like kinase 1 (PLK-1) is a crucial gene for cell viability in oral and colorectal cancer cells." (PMID 34830933, 2021).
colorectal cancer (continued). "In conclusion, BTF3 is positively related to CRC and BTF3-siRNA attenuated the tumorigenicity of colorectal cancer cells via MAD2L2, MCM3 and PLK1 activity reduction." (PMID 31263147, 2019). "In recent years, PLK1 inhibitors have demonstrated notable tumor reduction in highly proliferative CCND1-driven breast cancer bone metastases and improved oxaliplatin resistance levels in patients with advanced colorectal cancer." (PMID 37744268, 2023). "The functional significance of PLK1 in carcinogenesis and malignant progression is not clearly understood, but nonetheless its overexpression is found in many cancer types, including colorectal cancer." (PMID 26047016, 2015).
pancreatic cancer (65 papers, 2009 to 2025). "The expression of PLK1 has been uniquely associated with the differential response of human pancreatic cancer cells to PTEN regulation." (PMID 31979216, 2020). "Hence, elevated levels of PLK-1 can cause gemcitabine resistance in pancreatic cancer cells and xenograft tumor by restoring the blocked DNA synthesis." (PMID 28415805, 2017). "Nonetheless, the mechanism underlying PLK1 inhibition in pancreatic cancer remains unclear." (PMID 31979216, 2020). "In pancreatic cancer, PLK1 inhibition similarly upregulates PD-L1 expression but also enhances sensitivity to PD-L1 blockade, ultimately leading to tumor suppression." (PMID 40612941, 2025). "For example, targeting PLK1 has been shown to enhance the sensitivity of pancreatic cancer to immune checkpoint therapy." (PMID 41187171, 2025). "IGF2BP2 also binds to the m6A site of the PLK1 3'UTR in pancreatic cancer cells, upregulates the expression of PLK1, thereby maintaining cell cycle homeostasis and regulateing radiosensitivity." (PMID 39972266, 2025). "Further, PLK1 overexpression correlated with poor overall survival of patient outcomes in many types of cancers, including breast, liver, lung, kidney, and pancreatic cancers." (PMID 41404416, 2025). "Analysis by online website UALCAN revealed a positive correlation between PKMYT1 and PLK1 expression in pancreatic cancer cohorts (Fig. EV4F)." (PMID 38570712, 2024). "Further analysis using the public database GEPIA revealed that the expression of six genes (PLK1, SPC24, KIF2C, TOP2A, MKI67, and KIF4A) was significantly associated with overall survival in pancreatic cancer patients." (PMID 38250721, 2024). "Among these, PLK1, SPC24, KIF2C, TOP2A, MKI67, and KIF4A, have been implicated in cancer development and serve as important biomarkers of proliferative activity in pancreatic cancer." (PMID 38250721, 2024). "Suppression of PLK1 enhances the response of pancreatic cancer cells to immunotherapeutic strategies." (PMID 38953023, 2024). "One approach involves using superparamagnetic iron oxide nanoparticles coupled with PLK1-siRNA to specifically inhibit PLK1 expression and suppress pancreatic cancer cell proliferation." (PMID 38250721, 2024). "There is another report indicates that METTL3-mediated M6A modification involves in the prognosis and IR-induced alteration of cell cycle progressing of pancreatic cancer cells by targeting PLK1 mRNA 3’UTR." (PMID 38473842, 2024). "Studies have revealed the crucial role of M6A methylation of PLK1 in maintaining the cell cycle post-radiation in pancreatic cancer cells." (PMID 38473842, 2024). "Rigosertib impedes both Plk1-mediated G2–M cell-cycle transition and PLK-induced gemcitabine resistance in pancreatic cancer cells." (PMID 36975494, 2023). "This suggests that PLK1 methylation is essential for cell cycle maintenance in pancreatic cancer and is a new therapeutic target." (PMID 35773310, 2022). "This study revealed that METTL3 regulated cell cycle, especially mitosis, through the methylation of those genes in pancreatic cancer cells, and PLK1 was identified as a gene playing a central role in this process." (PMID 35773310, 2022). "By epitranscriptomic analysis, we report that polo-like kinase 1 (PLK1) is an important hub gene defining patient prognosis in pancreatic cancer and that RNA methylation is involved in regulating its cell cycle-specific expression." (PMID 35773310, 2022). "In pancreatic cancer, VRK2 phosphorylates and stabilizes cell cycle kinase Plk1, resulting in Plk1 overexpression to facilitate pancreatic cancer proliferation and chemotherapy resistance." (PMID 35911672, 2022). "In pancreatic cancer, Polo-like kinase 1 phosphorylation of ORC2 maintains DNA replication on gemcitabine treatment." (PMID 35711825, 2022).
pancreatic cancer (continued). "circ_0000977 was abnormally upregulated in pancreatic cancer, and silencing circ_0000977 inhibited pancreatic cancer cell proliferation and induced cell cycle arrest by stimulating miR-874-3p and inhibiting PLK1 expression." (PMID 34149924, 2021). "To verify the state of expression of ALDOA, ATM and PLK1 in patient tissues, we randomly selected 78 patients diagnosed with pancreatic cancer in our centre." (PMID 34565365, 2021). "In KRAS‐mutant pancreatic cancer cohort (n = 133), a strong correlation between PLK1 and FGF9, FGF14 was observed, and in KRAS‐mutant colon cancer (n = 170), only FGF14 strongly correlated with PLK1." (PMID 34369083, 2021). "PLK1, a tumorigenic factor, is a mitotic cyclin-independent serine threonine kinase that has been proposed as a potential therapeutic target for pancreatic cancer." (PMID 33224872, 2020). "Collectively, this study provides a rationale for targeting PTEN as an innovative therapeutic strategy based on the expression of PLK1 in pancreatic cancer patients." (PMID 31979216, 2020). "In the present study, we demonstrate the effect of PTEN blockade on human pancreatic cancer based on PLK1 expression in vitro and in vivo." (PMID 31979216, 2020). "Clinical evidence has also strongly indicated the critical role of PLK1 expression in pancreatic cancer prognosis based on PTEN expression." (PMID 31979216, 2020). "According to the alterations of the viability feature and intracellular signaling to the PTEN blockade following the over-expression or ablation of endogenous PLK1, we have suggested a novel function of PLK1 in human pancreatic cancer." (PMID 31979216, 2020). "Other targets of MIR296 are the proto-oncogenes AKT2 in pancreatic cancer, PLK1 in non-small cell lung cancer, SP1 in cervical cancer and CDX1 in gastric cancer." (PMID 32582296, 2020). "Soluble PLK1 has also been clearly detected in whole blood samples of pancreatic cancer patients when compared with healthy donors using Western blot analysis." (PMID 31979216, 2020). "Elevated expression of PTEN and expression of PLK1 have significantly aggravated the prognosis of pancreatic cancer patients, which suggests that PLK1 is a critical “signal informer” defining the clinical significance of PTEN expression." (PMID 31979216, 2020). "Targeting PTEN shows differential dependency on malignant features of pancreatic cancer through the expression levels of PLK1." (PMID 31979216, 2020). "The expression level of PLK1 renders differential clinical outcomes of PTEN highly expressed pancreatic cancer patients." (PMID 31979216, 2020). "In this study, we initially identified a combination of prognostic markers, miR-34a and PLK1, that showed better OS in pancreatic cancer patients." (PMID 29295989, 2018). "Here the authors produce a PGA-based polymeric nanocarrier for the dual delivery of miR-34a-mimic and PLK1-targeting siRNA resulting in killing of pancreatic cancer cells in vivo." (PMID 29295989, 2018). "In pancreatic cancer, PLK-1 acts as a mediator for inducing gemcitabine resistance (replication poison)." (PMID 28415805, 2017). "In our study, by inhibiting the PLK1 expression via mir3686 mimic, we observed the reduced proliferation of pancreas cancer as well." (PMID 26090465, 2015). "Our data suggested that inhibiting the mir3686 via its inhibitor did enhance the cell proliferation and colony formation, which is consistent with previous report about the role PLK1 played in pancreas cancer." (PMID 26090465, 2015). "In our previous study, we knocked down PLK-1 production in pancreatic cancer cells by utilizing siRNA transfection, and observed enhanced chemosensitivity to therapeutic agents." (PMID 19775446, 2009). "Interestingly, a study in pancreatic cancer discovered that ORC2 phosphorylation by polo-like kinase 1 promotes DNA replication under stress conditions and contributes to gemcitabine resistance, suggesting its potential importance in cancer progression." (PMID 40316534, 2025).
pancreatic cancer (continued). "Additionally, PLK1 inhibitors have been shown to enhance the sensitivity of pancreatic cancer to chemotherapy." (PMID 40612941, 2025). "Targeting PLK1 has emerged as a potential therapeutic strategy for pancreatic cancer." (PMID 38250721, 2024). "Polo-like kinase 1 (PLK1) serves as a pivotal prognostic regulator in pancreatic cancer patients." (PMID 38473842, 2024). "Functional analysis of PLK1 in pancreatic cancer cells showed that NMS-P937, a PLK1 inhibitor, could efficiently induce G2/M arrest, and along with radiation, it had a synergistic effect by increasing DNA double strand breaks." (PMID 35773310, 2022). "PLK1 expression was also found to be high in early stages of liver and pancreatic cancers." (PMID 36675706, 2022). "Among the top five genes, PLK1 was reported to be closely correlated with pancreatic cancer." (PMID 34485300, 2021). "Next, we administered phospho-PLK1-T210 to determine whether ATM inhibits PLK1 activation in human pancreatic cancer cells." (PMID 34565365, 2021). "PTEN and PLK1 is the companion biomarker in pancreatic cancer." (PMID 31979216, 2020). "Elevated PTEN expression has been specifically associated with a poor prognosis of pancreatic cancer in PLK1-expressing GSE17891 data set compared with a PLK1 non-expressing data set." (PMID 31979216, 2020). "However, further study should be performed to validate the correlation between PTEN and PLK-1 expressions in human pancreatic cancer cells." (PMID 31979216, 2020). "The prognostic value of PTEN also depends on PLK1 expression in pancreatic cancer." (PMID 31979216, 2020). "Ultimately, the uPICs exert significant antitumour activity for a spontaneous pancreatic tumour model and an orthotopic brain tumour model by transporting an apoptosis-inducing siRNA coding polo-like kinase 1 (PLK1) and an ASO coding turine upregulated gene 1 (TUG1), respectively." (PMID 31019193, 2019). "Interestingly, a recent study in pancreatic cancer cells showed that PLK1 inhibition enhances the effect of gemcitabine, also in gemcitabine‐resistant cells." (PMID 28556483, 2017). "In conclusion, our study demonstrated that mir3686 is the new regulator of the PLK1 and PLK1 inhibition via mir3686 and could be used as a new target for pancreas cancer therapy." (PMID 26090465, 2015). "Taken together, our results indicated that mir3686 could target PLK1 to inhibit the cell proliferation in pancreas cancer derived cell line and mir3686 could be a new therapeutic target for pancreas cancer treatment." (PMID 26090465, 2015). "Since there were reports that implied the role played by PLK1 in pancreatic cancer and indicated the PLK1 can be targeted by miRNA, we first checked the expression level of mir3686 and its relation with the PLK1 expression in a pancreatic carcinoma derived cell line PANC1 cell." (PMID 26090465, 2015). "The results suggested that the expression levels of PLK1 mRNA were higher in bladder, brain and CNS (Central Nervous System), colorectal, gastric, breast, esophageal, cervical, head and neck, ovarian, lung, liver, pancreatic cancer and lymphoma, sarcoma, leukemia compared to the normal tissues." (PMID 36618405, 2022). "In addition, we investigated whether soluble PLK1 may be detected in whole blood samples of pancreatic cancer patients to stratify patients for PTEN targeting." (PMID 31979216, 2020). "However, rephrasing differently, the high expression of PLK1 may represent an Achilles’ tendon for treating pancreatic cancer targeting the PTEN strategy." (PMID 31979216, 2020). "In addition to a previous report that demonstrated that overexpression of PLK1 had been observed in the early stage of pancreas cancer, our data suggested that PLK1 might be a promising target for the treatment of pancreas cancer." (PMID 26090465, 2015).